CASP1 (caspase 1)
Diseases named in the same sentence as CASP1 in open-access papers (continued):
Sharing a sentence is not in itself a finding about the gene and the disease.
diabetic cardiomyopathy (28 papers, 2014 to 2025). Diabetic cardiomyopathy is a disorder of the heart muscle in people with diabetes. "Another gene, encoding Glycoprotein Hormone Beta 5 (GBP5) is an inflammasome protein regulator that is implicated in caspase-1 dependent cell death and pyroptosis in diabetic cardiomyopathy." (PMID 37019881, 2023). "In diabetic cardiomyopathy, increased levels of caspase-1 related circRNAs activate Caspase-1 activity and cause pyroptosis, while silencing caspase-1 related circRNAs significantly reduces pyroptosis." (PMID 35647057, 2022). "Caspase-1-associated circRNA (CACR) likely leads to diabetic cardiomyopathy (DCM) pyroptosis via the miR-214-3p/caspase-1 pathway." (PMID 35880571, 2022). "Moreover, it was suggested that activation of AMPK phosphorylation ameliorates the alleviation of caspase-1-associated pyroptosis in in vivo and in vitro models of diabetic cardiomyopathy." (PMID 35642042, 2022). "SMI can inhibit the high-fat-induced activation of the NLRP3/Caspase-1 signaling pathway, intervene in cardiomyocyte pyroptosis, and prevent diabetic cardiomyopathy." (PMID 38027923, 2023). "Elmadbouh I and Singla DK found that diabetic cardiomyopathy involves sterile inflammation and causes the upregulation of NLRP3-Nek7-GBP5 inflammasome complex, which finally initiates Caspase-1-dependent pyroptosis in diabetic cardiomyopathy." (PMID 35509275, 2022). "Inhibition of Caspase-1 reduced the occurrence of cardiac fibrosis in diabetic cardiomyopathy and improved cardiac function via regulation of miR-135b." (PMID 35509275, 2022). "As previously noted, circ_0076631 regulated caspase-1 to mediate pyroptosis of diabetic cardiomyopathy." (PMID 36147837, 2022). "Western blotting analysis demonstrated that Puer-V significantly suppressed the NLRP3-Caspase-1-GSDMD signaling pathway which was highly activated in the diabetic cardiomyopathy." (PMID 36361807, 2022). "BMP-7 treatment showed protective effects against pyroptotic protein expression compared to the diabetic cardiomyopathy, as indicated by a significant reduction (p < 0.001) in caspase-1 levels." (PMID 34685620, 2021). "As reported in a previous study, phosphorylation of AMPK (pAMPK) was reduced in diabetic cardiomyopathy mice and high glucose-treated cardiomyocytes, and inflammation and pyroptosis markers such as caspase-1 and IL-1β were significantly increased." (PMID 34122131, 2021). "Metformin increased pAMPK and decreased caspase-1 and IL-1β expression, thereby improving the symptoms of diabetic cardiomyopathy." (PMID 34122131, 2021). "Moreover, KCNQ1OT1 aggravated fibrosis and pyroptosis in diabetic cardiomyopathy by targeting the miR-214-3p/caspase-1/TGF-β1/smad pathway." (PMID 36278219, 2022). "In addition, caspase-1-associated circRNA was reported to act as an miR-214-3p sponge to activate the caspase-1 dependent pathway to trigger pyroptosis in diabetic cardiomyopathy, and previous studies clarified that circRNAs play a vital role in pyroptosis." (PMID 35812182, 2022). "In the present study, we investigated a novel signaling target in diabetic cardiomyopathy where inflammation induces caspase-1-dependent cell death, pyroptosis, involving Nek7-GBP5 activators to activate the NLRP3 inflammasome, destabilizes cardiac structure and neovascularization." (PMID 34685620, 2021). "Recent evidence has shown that high glucose could promote NLRP3 inflammasome-mediated collagen synthesis, leading to caspase 1 activation and IL-1β secretion, which ultimately contribute to cardiac fibrosis in diabetic cardiomyopathy." (PMID 31354519, 2019). "Therefore, the present study investigates whether diabetic cardiomyopathy involves sterile inflammation and causes the upregulation of NLRP3-Nek7-GBP5 inflammasome complex, which finally initiates caspase-1-dependent pyroptosis in diabetic cardiomyopathy." (PMID 34685620, 2021).
diabetic cardiomyopathy (continued). "However, it is undeniable that the effect of mir-30d on diabetic cardiomyopathy may be mediated by a variety of mechanisms in addition to the foxo3a–ARC–caspase-1 pathway, and further investigation is required to unveil the other mechanisms involved." (PMID 25341033, 2014). "LncRNA GAS5 is down-regulated in cardiomyocytes with diabetic cardiomyopathy (DCM), and its overexpression suppresses the expression of NLRP3 and its downstream genes and caspase-1 activity, thus improving DCM." (PMID 37498354, 2023). "Furthermore, the treatment of type two diabetes mellitus model mice with 100 mg/kg/day ticagrelor for 12 weeks attenuated the progression of diabetic cardiomyopathy and reduced the expression levels of NLRP3, caspase-1, and GSDMD-N in the myocardium." (PMID 38188139, 2024). "In this study, we found that miR-223-3p, as a regulator of the pyroptosis molecule NLRP3, is downregulated in the myocardium of diabetic cardiomyopathy mice, but significantly increased after MSC treatment, thereby reducing the protein levels of NLRP3, Caspase-1, GSDMD, and IL-1β." (PMID 38956716, 2024).
hepatocellular carcinoma (28 papers, 2015 to 2026). A malignant tumor that arises from hepatocytes. "In hepatocellular carcinoma, sorcin is considerably upregulated and caspase-1, GSDMD-N and IL-1β are significantly decreased." (PMID 39616223, 2024). "The antimalarial drug dihydroartemisinin (DHA) activated AIM2/caspase-1 inflammasomes and induced autophagy, thereby suppressing hepatocellular carcinoma growth." (PMID 32703253, 2020). "Accumulating data indicate caspase-1 (CASP1), one of the inflammatory caspases, promotes hepatocellular carcinoma (HCC) progression in tumor proliferation, invasion, EMT phenotype and sorafenib resistance." (PMID 33168816, 2020). "A recent study showed that 17β-estradiol suppressed hepatocellular carcinoma progression by inducing caspase-1-mediated pyroptosis and inhibiting autophagy." (PMID 32703253, 2020). "In hepatocellular carcinoma cells, hypoxia induces caspase-1 activation, cleavage and release of proinflammatory cytokines, IL-1β and IL-18." (PMID 29184853, 2017). "Moreover, galunisertib 35 triggers the pyroptotic pathway in glioblastoma, pancreatic cancer, and hepatocellular carcinoma through caspase-1/GSDMD activation." (PMID 39316325, 2025). "In accordance with our results, caspase 3 was recently shown to be weakly expressed in intact hepatocellular carcinoma HepG2 cells, supporting earlier findings documenting the lower expression of caspase 1 and caspase 3 in hepatocellular carcinoma tissue compared to nontumor cells." (PMID 36838715, 2023). "Luan and Ju discovered that activated caspase-1 could stimulate hepatoma cells to pyroptosis, release proinflammatory cytokines, and further promote the growth of HCC." (PMID 35782053, 2022). "Based on these studies, we hypothesised that GGA stimulates TLR4 signalling to induce UPR, activates CASP1, and then induces pyroptotic cell death in human hepatoma cells." (PMID 32270855, 2020). "Lower levels of caspase-1, IL-1β, and IL-18 were observed in hepatocellular carcinoma (HCC) tissues compared with adjacent normal ones, implying the role of pyroptosis in tumorigenicity." (PMID 35432318, 2022). "The YT strain infection was associated with the activation of Toll-like receptors (TLRs), nuclear factor kappa B (NF-κB), caspase-1, and NOD-like receptors (NLRs) in the liver and primary hepatocellular carcinoma epithelial cells (LMH)." (PMID 37063902, 2023). "Further studies revealed that conjugated BAs induced pyroptosis through increasing cleaved-Caspase-1 and cleaved-GSDMD protein expression in human hepatoma PLC/RPF/5-ASBT cells and primary mouse hepatocytes, which was further confirmed by TEM analysis." (PMID 36690641, 2023). "We previously reported that cotreatment with Ac-YVAD-CMK, a CASP1-specific inhibitor, blocks GGA-induced cell death in human hepatoma cells." (PMID 32270855, 2020). "In addition to priming tumoricidal activity of hepatic NK cell, NLRP3 inflammasome also induces caspase-1-mediated pyroptosis to control the proliferation of hepatocellular carcinoma (HCC) cells." (PMID 30319645, 2018). "In a preclinical model of hepatocellular carcinoma (HCC), estrogen receptor signaling increased cancer cell death through NLRP3 inflammasome-initiated, caspase-1-dependent pyroptosis and inhibition of autophagy in cancer cells." (PMID 33572196, 2021). "Indeed, in contrast to our study, estrogens were reported to inhibit NLRP3 inflammasome pathway activation, caspase-1, and proinflammatory cytokine production in the brain after global cerebral ischemia, while activating NLRP3 inflammasome and triggering pyroptosis in hepatocellular carcinoma cells." (PMID 39654901, 2024). "Resaerchers have reported that luteoloside suppresses hepatocellular carcinoma cells (HCC) through the inhibition of HCC migration and invasion and has the capacity to downregulate the expression level of NLRP3, caspase-1 and IL-1β, suppressing proliferation and metastasis of HCC." (PMID 32650482, 2020).
lung cancer (28 papers, 2014 to 2025). A malignant neoplasm involving the lung. "In lung cancer, drugs induce pyroptosis by activating the caspase-1- GSDMD signaling pathway to inhibit tumor growth, though the specific mechanisms vary." (PMID 39994107, 2025). "Bioinformatics analysis revealed that caspase-1 expression is generally lower in lung cancer and is inversely correlated with HOXC8 expression." (PMID 40701951, 2025). "Bufalin decreases NCI-H460 cell activity in lung cancer and blocks tumor cells in the G0/G1 and G2/M phases, promoting apoptosis by increasing the production of oxygen-free radicals, caspase-1, and caspase-9." (PMID 32148531, 2020). "Considering the anti-apoptosis capability of BCL2 families, we assessed the apoptosis/pyroptosis of A549 lung cancer cells by detecting the expression of the cleaved Caspase-3 and Caspase-1, respectively." (PMID 31508368, 2019). "NLRP3 inflammasome components NLRP3, ASC, and Caspase-1 were found to be highly expressed in lung cancer cell lines and tissues than in adjacent normal tissues." (PMID 28865486, 2017). "In contast to cholangiocarcinoma or lung carcinoma, keratinocytes are known to carry functional inflammasomes which activate caspase-1 to induce IL-1 secretion." (PMID 27768771, 2016). "Simvastatin, a classical anti-hyperlipidemic drug, was reported to induce pyroptosis by activating the NLRP3 inflammasomes caspase-1-IL-18 and IL-1β axes in H1299 and A549 lung cancer cell lines without causing poisonousness tohealthy lung cells." (PMID 38016064, 2023). "Wang had found that caspase-1 dependent pyroptosis induced by the lipid-lowering drug simvastatin occurred in lung cancer cells, indicating that simvastatin might be a potential drug for clinical treatment of NSCLC." (PMID 37194012, 2023). "In addition, the levels of NLRP3, cleaved caspase-1, IL-1β and IL-18 were increased in the two lung cancer cells with miR-223-3p inhibition, and the corresponding results were contrary in miR-223-3p mimic group." (PMID 36276078, 2022). "Besides, the levels of NLRP3, cleaved caspase-1, IL-1β and IL-18 were increased in the two lung cancer cells." (PMID 36276078, 2022). "Although MCC950, a potent small molecule inhibitor of NLRP3 inflammasome, was previously reported to inhibit survival, migration, and invasion in head, neck, and lung cancer, the effect of caspase-1 inhibitors, such as Ac-YVAD-cmk, on tumor growth remains controversial." (PMID 32155890, 2020). "The activation of NLRP3 inflammasome could promote the proliferation and migration of lung adenocarcinoma A549 cells by mediating the release of IL-18 and IL-1β through the caspase-1 dependent pyroptosis pathway, while blocking IL-18 and IL-1β signaling could inhibit the progression of lung cancer." (PMID 37194012, 2023). "NLRP3 inflammasome activation-induced IL-1β and IL-18 in lung cancer may work through mechanisms other than the caspase-1 pathway, indicating that NLRP3 inflammasome can mediate the release of IL-1β and IL-18 through caspase-1-dependent or -independent pathways." (PMID 33613533, 2020). "These epigenetic modifications suppress NLRP3 expression, inhibit the activation of the NLRP3- caspase-1- GSDMD pathway, and confer an anti-pyroptotic phenotype to lung cancer cells." (PMID 39994107, 2025). "As caspase-1 was the major downstream molecule of NLRP3 inflammasome, its inhibitor Z-YVAD-FMK attenuated LPS+ATP-induced A549 lung cancer cells proliferation." (PMID 34211462, 2021). "High expression of the BC-specific ICD-derived metagene signature (TNF/CXCR3/P2RX7/CASP1/NLRP3/IL1B/LY96/CD4+/CD8+A/CD8+B/PRF1/IFNG/IL17A/IL17RA) is associated with prolonged overall survival (OS) in BC and OC patients but not in lung cancer patients." (PMID 37445860, 2023).
lung cancer (continued). "Then, the migration and invasion of lung cancer cells were detected with miR-223-3p mimic and inhibitor using Transwell assay, at the same time the expression of NLRP3, cleaved caspase-1, IL-1β and IL-18 was determined using Western Blot and immunohistochemistry assay." (PMID 36276078, 2022). "For the genes in module m63, A2M was in limited and extended lung cancer patients compared to a nonsmoker and smoker control population, FABP4 was down-regulated in lung adenocarcinoma, and CASP1 affected the single-nucleotide polymorphisms, increasing the cancers risk." (PMID 24643254, 2014).
type 2 diabetes (28 papers, 2013 to 2025). "In the spinal cord, the NLRP3/Casp1/IL-1β inflammasome activation axis is associated with chronic itch in type 2 diabetes and IMQ-induced chronic itch models." (PMID 39867900, 2024). "Additionally, there was increased expression of caspase-1, a key enzyme that causes apoptosis, in these cells from patients with type 2 diabetes." (PMID 37106238, 2023). "Furthermore, the same study implicated that the level of caspase-1 expression was positively correlated with the severity of type 2 diabetes in individuals." (PMID 27842563, 2016). "In multivariable analysis, caspase-1 upregulation was independently associated with STEMI presentation and low-density lipoprotein-cholesterol, and IL-1β with type 2 diabetes." (PMID 41598157, 2025). "DAVID was used to identify the functions of these genes, and TIRAP, TNFRSF1A, CASP1, CSF1, and ITGAM were associated with type 2 diabetes." (PMID 39194753, 2024). "The mtDNA from patients with type 2 diabetes induced AIM2 inflammasome-dependent caspase-1 activation, and IL-1β and IL-18 secretion in macrophages." (PMID 30965677, 2019). "Spironolactone treatment reduced the activation of caspase-1 and mature IL-1β content in arteries taken from mice with type 2 diabetes." (PMID 31817997, 2019). "One research of type 2 diabetes has shown that the maturation of caspase-1 and IL-1β, the sign of NLRP3 inflammation activation, did not required TXNIP in bone marrow-derived macrophages." (PMID 25136835, 2014). "In addition, D-ribose promotes NLRP3 inflammasome activation in type 2 diabetes to induce podocyte injury and glomerulosclerosis, the caspase-1 inhibitor YvAD significantly blocks podocyte injury." (PMID 36387904, 2022). "However, some researchers have found that FS is associated with an increased incidence of type 2 diabetes, impairs insulin signaling, and worsens insulin resistance, inducing inflammatory responses by the NLRP3/caspase-1 pathway." (PMID 30939798, 2019). "We analyzed caspase-1 activation and the IL-1β and IL-18 secretion in lipopolysaccharide (LPS)-primed bone marrow-derived macrophages (BMDMs) stimulated with ccf-DNA from patients with type 2 diabetes and poly(dA:dT), an AIM2 inflammasome activator." (PMID 30965677, 2019). "Furthermore, in the myeloid cells of type 2 diabetes, caspase-1 activation is observed." (PMID 31197747, 2019). "Notably, the ccf-DNA (ccf-DNA #1 and ccf-DNA #2) from two independent patients with type 2 diabetes resulted in a higher expression of cleaved caspase-1 and cleaved IL-1β in response to poly(dA:dT) stimulation compared with the vehicle control (control), although pro-IL-1β expression was unchanged." (PMID 30965677, 2019). "For type 2 diabetes PDN model, TBK1-siRNA, Caspase-1 inhibitor Ac-YVAD-cmk or TBK1 inhibitor amlexanox (AMX) were delivered by intrathecal injection or intragastric administration." (PMID 39030571, 2024). "Activation of the innate immune system has been shown relevant in the pathogenesis of type 2 diabetes mellitus (T2DM), and caspase-1 dependent IL-1 production has been demonstrated in macrophages isolated from fat tissue of patients with T2DM." (PMID 25784780, 2015). "Spironolactone treatment reduced the number of active caspase-1-positive-macrophages in the db/db mice, supporting the theory that aldosterone activates the NLRP3 inflammasome in the immune cells of mice with type 2 diabetes." (PMID 31817997, 2019). "We examined the expression of caspase-1 substrates in eight disease conditions including coronary artery disease (CAD), metabolic syndrome (MS), type 2 diabetes (T2D), morbidly obese (MO), rheumatoid arthritis (RA), and hypertension." (PMID 27842563, 2016). "The mtDNA, from patients with type 2 diabetes, induced absent in melanoma 2 (AIM2) inflammasome-dependent caspase-1 activation and IL-1β and IL-18 secretion in macrophages." (PMID 30965677, 2019).